CRTC1 (CREB regulated transcription coactivator 1)
Description:
Transcriptional coactivator for CREB1 which activates transcription through both consensus and variant cAMP response element (CRE) sites. Acts as a coactivator, in the SIK/TORC signaling pathway, being active when dephosphorylated and acts independently of CREB1 'Ser-133' phosphorylation. Enhances the interaction of CREB1 with TAF4. Regulates the expression of specific CREB-activated genes such as the steroidogenic gene, StAR. Potent coactivator of PGC1alpha and inducer of mitochondrial biogenesis in muscle cells. In the hippocampus, involved in late-phase long-term potentiation (L-LTP) maintenance at the Schaffer collateral-CA1 synapses. May be required for dendritic growth of developing cortical neurons (By similarity). In concert with SIK1, regulates the light-induced entrainment of the circadian clock. In response to light stimulus, coactivates the CREB-mediated transcription of PER1 which plays an important role in the photic entrainment of the circadian clock. (Microbial infection) Plays a role of coactivator for TAX activation of the human T-cell leukemia virus type 1 (HTLV-1) long terminal repeats (LTR).
Synonyms: TORC-1; KIAA0616; MECT1; TORC1; WAMTP1; FLJ14027; MAML2; Mam-2
Tractability: Antibody: its Gene Ontology location is reachable by antibodies, with high confidence. PROTAC: ubiquitination databases record sites on it; its protein half-life has been measured.
Gene: Protein-coding gene on chromosome 19 (18,683,640 to 18,782,333, forward strand). Ensembl gene ENSG00000105662.
Subcellular location: Cytoplasm; Nucleus
Subcellular location (Human Protein Atlas): Cytosol; Nuclear bodies; Plasma membrane; Nucleoplasm
Pathways (Reactome):
Circadian clock: Expression of BMAL (ARNTL), CLOCK, and NPAS2; Phosphorylated BMAL1:CLOCK (ARNTL:CLOCK) activates expression of core clock genes
Cellular responses to stimuli: Heme signaling
Organelle biogenesis and maintenance: Transcriptional activation of mitochondrial biogenesis
Gene Ontology:
Molecular function: cAMP response element binding protein binding; protein binding; transcription coactivator activity
Biological process: positive regulation of transcription by RNA polymerase II; cellular response to cAMP; entrainment of circadian clock by photoperiod; protein homotetramerization
Cellular component: cytoplasm; cytosol; nuclear body; nucleoplasm; nucleus
Genetic constraint (gnomAD): Loss-of-function variants: 14 observed, 52.52 expected, observed/expected ratio (o/e) 0.27, 90% interval 0.17 to 0.42. The upper end of that interval is the gene's LOEUF score, 0.42, which puts it in group 1 of 6, group 1 being the genes least tolerant of losing a copy. Missense variants: 619 observed, 777.02 expected, observed/expected ratio (o/e) 0.8, 90% interval 0.75 to 0.85. Synonymous variants: 394 observed, 355.37 expected, observed/expected ratio (o/e) 1.11, 90% interval 1.02 to 1.21.
Cancer hallmarks: proliferative signalling (promotes)
Homologues: Orthologues: chimpanzee CRTC1 (99% identical), macaque CRTC1 (99% identical), dog CRTC1 (96% identical), pig CRTC1 (94% identical), mouse Crtc1 (90% identical), rat Crtc1 (90% identical), guinea pig CRTC1 (89% identical), tropical clawed frog crtc1 (78% identical), zebrafish crtc1b (61% identical), zebrafish crtc1a (59% identical), Drosophila melanogaster Crtc (27% identical), Caenorhabditis elegans crtc-1 (20% identical). Paralogues in human: CRTC2 (41% identical), CRTC3 (35% identical).
Diseases named in the same sentence as CRTC1 in open-access papers:
CRTC1 is named in the same sentence as 145 diseases in open-access papers, as found by Europe PMC text mining. Sharing a sentence is not in itself a finding about the gene and the disease. The quoted sentences say what the papers report.
Obesity (19 papers, 2010 to 2025). Accumulation of substantial excess body fat. "CRTC1 polymorphisms seem to play a role with obesity markers in individuals diagnosed with lifetime MDD rather than non-depressive individuals.No direct association of CRTC1 polymorphisms with MDD in the three samples tested." (PMID 35242012, 2022). "Several human studies evaluated the association of CRTC1 single nucleotide polymorphisms (SNPs) with obesity markers in the general population." (PMID 35242012, 2022). "Several studies have identified a relationship between CRTC1 polymorphisms and psychiatric disorders, with focus on obesity parameters and stress." (PMID 36224260, 2022). "The area of adipocytes, in particularly eWAT, showed a uniform and significant increase in Crtc1–/– mice confirmed by H&E staining, suggesting that the impact of Crtc1 deficiency on obesity was specific to white adipose tissues." (PMID 33912553, 2021). "In summary, our data demonstrate that the obesity caused by Crtc1–/– deficiency was associated with increased fat accumulation in white adipose tissues, which potentially via activating PPARγ signaling pathway." (PMID 33912553, 2021). "CRTC1 deficiency may contribute to insulin resistance and obesity by dysregulating glucose and lipid metabolism." (PMID 40977688, 2025). "Moreover, CRTC1 seems necessary to protect against hepatic steatosis, which is strongly associated with obesity and metabolic syndrome, and to modulate leptin’s glucoregulatory actions in insulin-dependent diabetes." (PMID 35242012, 2022). "An interaction between CRTC1 SNP and sex was also observed in a human study that examined whether the CRTC1 polymorphism was associated with obesity markers in subjects with lifetime depression." (PMID 35242012, 2022). "However, a direct causality between Crtc1 deficiency and reduced hypothalamic Bdnf transcripts in the development of obesity is still elusive, and therefore, further molecular and behavioral researches are required." (PMID 35242012, 2022). "Finally, we highlight rodent and human studies supporting the critical involvement of CRTC1 in depression-associated obesity." (PMID 35242012, 2022). "Nevertheless, whether Crtc1 deficiency affects peripheral tissues during the development of obesity remains unclear." (PMID 33912553, 2021). "We previously investigated whether CRTC1 deficiency in PVH (Sim1 cells) could cause obesity." (PMID 35020776, 2022). "Therefore, alterations in liver metabolism might still be present, and its contribution to the obesity in Crtc1-deficient mouse need to be further investigated in future." (PMID 33912553, 2021). "Whether the obesity caused by Crtc1 deletion links to Pparγ remains unexplored." (PMID 33912553, 2021). "In conclusion, improved knowledge of the mechanisms through which CRTC1 synchronizes metabolic functions with the light cycle may facilitate our understanding of the biological processes underlying the interaction between obesity and depression." (PMID 29217834, 2017). "We previously generated a Crtc1−/− mouse line using CRISPR/Cas9 and found that Crtc1 deficiency caused spontaneous obesity through regulating the PPARγ pathway." (PMID 38644501, 2024). "As male Crtc1−/− mice show a stronger depressive-like phenotype with a more severe comorbid obesity than females, we decided to capitalize on the former to focus on mechanistic aspects rather than sex differences in our neuroimaging study." (PMID 36224260, 2022). "Crtc1–/– mice exhibited hyperphagia and body weight gain from early adult age with consequent development of obesity." (PMID 35242012, 2022). "This review will focus on the increasing evidence of the key role of the transcription coactivator CRTC1 in the central control of mood and eating behavior, and its possible involvement in depression and comorbid obesity." (PMID 35242012, 2022). "In accordance with this broad function, the genetic suppression of CRTC1 in the mouse was found to induce depressive-like symptoms and obesity." (PMID 35242012, 2022).
Obesity (continued). "This study showed that mice with a ventromedial hypothalamus-specific knockdown of Crtc1 are sensitive to high-fat diet-induced obesity, exhibiting hyperphagia and increased body weight gain, but have a normal feeding behavior with a control chow diet." (PMID 35242012, 2022). "Genome-wide DNA methylation analysis and pyrosequencing confirmation revealed that the methylation levels of 2 CpG sites in CRTC1 were significantly changed in patients with obesity compared with normal controls." (PMID 35242012, 2022). "Deletion of Crtc1 gene in mice induces insulin resistance and obesity, together with a depressive-like phenotype." (PMID 35242012, 2022). "This review focuses on recent evidence emphasizing the critical role of CRTC1 in the neurobiology of depression and comorbid obesity." (PMID 35242012, 2022). "The results excluded the possibility that abnormal food intake or reduced energy expenditure is the main contribution to obesity in Crtc1–/– mice." (PMID 33912553, 2021). "Reduced hypothalamic expression of anorexigenic neuropeptide genes is one of the reasons that Crtc1–/– mice manifest obesity." (PMID 33912553, 2021). "In this study, we firstly identified transcription cofactor Crtc1 as one of genes to generate anti-obesity effect, reflected by increase of bodyweight and fat weight including sWAT, eWAT and BAT in Crtc1–/– mice." (PMID 33912553, 2021). "Our findings demonstrate a crucial role of Crtc1 in regulating lipid metabolism in adipose during development, and provide novel insights into obesity prevention and therapeutics." (PMID 33912553, 2021). "In conclusion, these data suggest that the obesity of Crtc1 mutant males depends, at least in part, on increased food consumption during the resting phase." (PMID 29217834, 2017). "Altogether, these findings suggest that CRTC1 is a transcriptional coactivator reciprocally involved in the bidirectional relation between obesity and depression." (PMID 29217834, 2017). "Accordingly, Crtc1 KO mice developed spontaneous hepatic steatosis and systemic insulin resistance in young age before they developed an apparent sign of obesity, which are indicative of intrinsic metabolic defects in their peripheral tissues." (PMID 27869139, 2016). "In congruence with this study, Crtc1 KO mice displayed symptoms of obesity, including increased weight gain and visceral adiposity, on a standard chow diet at as early as 9–10 weeks of age (not shown)." (PMID 27869139, 2016). "In addition, multiple lines of evidence highlight the critical role of CRTC1 in linking the comorbid neurobiological mechanisms of depression and obesity." (PMID 39000495, 2024). "Even though Crtc1 is predominantly expressed in the brain deleting this gene in mice induces a systemic metabolic deregulation, such as insulin resistance and obesity, together with a depressive-like phenotype." (PMID 36224260, 2022). "Mice with a ventromedial hypothalamus (VMH)-specific knockdown of Crtc1 are sensitive to high-fat diet-induced obesity, exhibiting hyperphagia and increased body weight gain.Unlike Crtc1–/– mice, VMH-specific Crtc1 deletion did not affect body weight gain or food intake in normal chow feeding." (PMID 35242012, 2022). "Although the human CRTC1 polymorphisms studied so far were not clearly associated with depression, they were associated with obesity markers [body mass index (BMI), fat mass] in psychiatric cohorts and in individuals with MDD." (PMID 35242012, 2022). "With regard to obesity, further human genetic investigations showed that the CRTC1 locus links fat mass to cardiometabolic diseases and that genetic and epigenetic control of CRTC1 transcription affects fat distribution and eating behavior." (PMID 35242012, 2022). "Cumulating clinical and animal studies emphasize that the disruption of circadian rhythm widely affects lipid metabolism and accelerates the occurrence and development of obesity, which may be the crucial reason for the obesity in Crtc1–/– mice." (PMID 33912553, 2021).
Obesity (continued). "Whether the impaired fertility of Crtc1–/– mice is a result of obesity per se needs to be investigated in future." (PMID 33912553, 2021). "Another possible contributor to obesity may be derived from the impact of Crtc1 on food absorption, which needs validation in future studies." (PMID 33912553, 2021). "Crtc1–/– mice exhibit hyperphagia, obesity, infertility and cardiac hypertrophy." (PMID 33912553, 2021). "Overexpression of CRTC1 in mice led to obesity and infertility." (PMID 32047514, 2019). "For example, of the four loci discovered by the recently discussed GWAS in BF% (in or near COBLL1/GRB14, IGF2BP1, PLA2G6, CRTC1) and in the most recent GWAS of obesity as measured by BMI only a very small number of these overall obesity loci exhibited sexual dimorphism (approximately 3–5%)." (PMID 28073971, 2017). "We compared ARC gene expression in 8-week-old and 36-week-old Crtc1−/− and WT males, as well as the relative expression of four anorexigenic genes (LepRb, Cart, Nor1, and Glp-r1), three orexigenic genes (AgRP, Npy, and Npy-y1) and the fat-mass-related and obesity-related gene (Fto)." (PMID 29217834, 2017). "We found that Sim1 cell-specific CRTC1 and CRTC2 double-knockout mice were sensitive to high-fat diet (HFD)-induced obesity." (PMID 35020776, 2022). "Altogether, these observations strengthen the hypothesis that CRTC1 may represent a pivotal transcription coactivator regulating both MDD and obesity etiological pathways." (PMID 35242012, 2022). "The development of obesity in Crtc1–/– mice is independent of alterations in food intake or energy expenditure." (PMID 33912553, 2021). "In this study, we further investigated the consequences of the lack of CRTC1 on the energy balance of Crtc1−/− male and female mice, with the aim of better defining CRTC1-regulated molecular pathways involved in obesity, and possibly in mood disorders as well." (PMID 29217834, 2017). "Mutant males were hyperphagic and rapidly developed obesity on normal chow diet, whereas Crtc1−/− females exhibited mild late-onset obesity without hyperphagia." (PMID 29217834, 2017). "Crtc1 KO mice were significantly more glucose intolerant and insulin resistant than their wild-type littermates, suggesting that Crtc1 KO mice may have intrinsic, not necessarily obesity-dependent, defects in their peripheral tissue functions to maintain systemic metabolic homeostasis." (PMID 27869139, 2016).
mucoepidermoid carcinoma (18 papers, 2018 to 2025). A carcinoma morphologically characterized the presence of cuboidal mucous cells, goblet-like mucous cells, squamoid cells, cystic changes, and a fibrotic stromal formation. "Interestingly, the presence of CRTC1::MAML2 gene fusion in thymic mucoepidermoid carcinomas was associated with classic tumor histology, lower pT and TNM stage, and better overall survival." (PMID 38067300, 2023). "CRTC1 forms fusion transcripts with mastermind-like 2 (MAML2) that function as transcriptional coactivators driving mucoepidermoid carcinoma development, including in lungs." (PMID 40977688, 2025). "For instance, in mucoepidermoid carcinomas, the reported fusion gene is cysteine-rich C-terminal 1 (CRTC1) leading to MAML2::CRTC1 fusions." (PMID 38067300, 2023). "Previously reported gene translocations and fusion oncogenes include the CRTC1/3-MAML2 fusion gene in mucoepidermoid carcinoma and the MYB-NFIB fusion gene in adenoid cystic carcinoma." (PMID 36431032, 2022). "These include fusions of the ETV6 gene in secretory carcinoma (SC), MYB/MYBL1::NFIB in adenoid cystic carcinoma (AdCC), CRTC1/CRTC3::MAML2 in mucoepidermoid carcinoma (MEC), and EWSR1::ATF1 in hyalinizing clear cell carcinoma as the most frequent and best characterized gene fusions." (PMID 38217715, 2024). "Similarly, CRTC1::MAML2 fusions have been described in mucoepidermoid carcinoma of various sites, whereas CRTC1::SS18 fusion has been implicated in a subset of undifferentiated small round blue cell sarcomas CMTCT have only been reported in CMTCT." (PMID 36726909, 2022). "In addition, fluorescence in situ hybridization is used for the detection of fusion genes, such as the ETV6-NTRK3 fusion gene in secretory carcinoma and the CRTC1/3-MAML2 fusion gene in mucoepidermoid carcinoma." (PMID 34919590, 2021). "Salivary gland mucoepidermoid carcinoma (MEC) is a morphologically challenging tumor, harboring a canonical CRTC1/3:MAML2 fusion, if investigated." (PMID 40478494, 2025). "In our case, only the CRTC1::MAML2 fusion found in molecular biology allowed us to make the differential diagnosis and conclude that it was a mucoepidermoid carcinoma." (PMID 39677248, 2024). "Studies in mice have confirmed CRTC1::MAML2 as an oncogenic driver for the development and maintenance of mucoepidermoid carcinomas." (PMID 38067300, 2023). "However, mucoepidermoid carcinoma is often characterized by the fusion of the CRTC1 and MAML2 genes, which is not a feature of HCCC." (PMID 40738062, 2025).